PTPN11 (protein tyrosine phosphatase non-receptor type 11)
Diseases named in the same sentence as PTPN11 in open-access papers (continued):
Sharing a sentence is not in itself a finding about the gene and the disease.
Noonan syndrome (continued). "Interestingly, the Ras-activating PTPN11 (SHP2) p.Tyr63Cys variant identified in KVOGM23-1 was previously identified in Noonan syndrome (OMIM# 163950), which features a broad spectrum of congenital heart defects and other systemic vascular lesions." (PMID 37978175, 2023). "Furthermore, the PTPN11 gene causes Noonan syndrome, accounting for approximately 50% of cases of this genetic disorder." (PMID 37265961, 2023). "Mutations in PTPN11, a human orthologue of csw, account for more than half of Noonan syndrome." (PMID 36897069, 2023). "Importantly, patients with PTPN11 mosaicism theoretically risk passing on the variant to their children as the germline RASopathy Noonan syndrome with lentigines." (PMID 36566878, 2023). "As is known, Noonan syndrome and phenotypically overlapping syndromes such as Costello syndrome and Leopard syndrome are part of the so-called rasopathies and are caused by at least 16 genes, PTPN11 and HRAS are the most prevalent genes." (PMID 37660152, 2023). "Pulmonary valve stenosis is the most common CHD in Noonan syndrome patients with PTPN11 mutations." (PMID 36496429, 2022). "Primary brain tumors in Noonan syndrome with PTPN11 mutations." (PMID 36060964, 2022). "Cardiac anomalies in 32 patients with Noonan syndrome, diagnosed with PTPN11 variants." (PMID 36160796, 2022). "Interestingly, patients with PTPN11 mutation present significantly higher prevalence of pulmonary valve stenosis, named Noonan syndrome." (PMID 36212153, 2022). "The mutations of the PTPN11 gene have been identified in Noonan syndrome and LEOPARD syndrome." (PMID 36496429, 2022). "Mutations in PTPN11 are associated with Noonan syndrome (NS)." (PMID 35245205, 2022). "In addition, the PTPN11 gene mutations are predominantly related to RASopathies, including Noonan syndrome (NS), and cognitive deficits such as learning disabilities are common in patients with NS." (PMID 34746237, 2021). "PTPN11 mutations are the most common cause of Noonan syndrome, a relatively common autosomal dominant disorder, classified as a RASopathy, a disorder of RAS signaling commonly associated with hypertrophic cardiomyopathy, or other malformations of the blood vessels." (PMID 34859065, 2021). "Importantly, more than 50% of patients with Noonan syndrome display a pathogenic mutation in the PTPN11 gene encoding SHP-2 protein." (PMID 34344467, 2021). "For example, PTPN11, the variations in PTPN11 are the primary cause of Noonan syndrome with multiple lentigines and Noonan syndrome, which have common skin and facial symptoms, cardiac abnormalities and growth retardation, and hearing loss is considered to be a rare feature in these patients." (PMID 34733322, 2021). "Hence, we established the diagnosis of a Noonan syndrome and concluded that the de novo PTPN11 variant predisposed for the leukemia onset in Case-68." (PMID 33840814, 2021). "Infants with Noonan syndrome are at risk for several hematologic abnormalities including bleeding secondary to coagulation defects and myeloproliferative disorders mostly associated with PTPN11 mutations." (PMID 32396283, 2020). "This case of Noonan syndrome with PLE was associated with a PTPN11 mutation." (PMID 32054441, 2020). "Intriguing observations were made in a new mouse model of Noonan syndrome in which stromal mutations of Ptpn11 encoding the protein tyrosine phosphatase SHP2 fostered onset of juvenile myelomonocytic leukemia (JMML) which was previously deemed to be a cell-intrinsic defect." (PMID 32630305, 2020). "In the Noonan syndrome group, six had a PTPN11 mutation, one in RIT 1, and one SHOC-2 mutation; mutation status was unknown in three children." (PMID 33519543, 2020). "Noonan syndrome (NS) is an autosomal dominant disorder in some cases caused by PTPN11 mutations." (PMID 31637070, 2019).
Noonan syndrome (continued). "Meanwhile, prolonged activation of PI3K/AKT and ERK signaling disrupts the regulation of cell growth and division, leading to the characteristic features of Noonan syndrome (OMIM# 163950) that is caused by germline variation in KRAS genes (PTPN11, SOS1, RAF1, LZTR1, etc.)." (PMID 31752936, 2019). "Indeed, it also shares the main causative gene (PTPN11) with Noonan Syndrome, although the underlying molecular mechanisms are entirely different." (PMID 31722741, 2019). "Four patients who carried LGD variants in known DD genes (POGZ, ARID1B, FOXP1, and SIN3A) and one patient who carried a known activating variant in the Noonan syndrome gene PTPN11 were considered pathogenic variants by the American College of Medical Genetics and Genomics guidelines." (PMID 30532227, 2018). "Germline activating mutations of the protein tyrosine phosphatase SHP2 (encoded by PTPN11) positively regulate Ras signalling in 50% of Noonan syndrome patients, who have an increased risk of developing juvenile myelomonocytic leukaemia (JMML), a childhood myeloproliferative neoplasm (MPN)." (PMID 28942353, 2018). "The difference in molecular consequences between somatic and germline SETBP1 mutations is in line with findings from previous studies examining somatic and germline mutations in PTPN11, involved in juvenile myelomonocytic leukemia and in Noonan syndrome, respectively." (PMID 28346496, 2017). "Autosomal-dominant mutations in Ptpn11, which have been detected in approximately half of the patients with Noonan syndrome, predispose affected individuals to juvenile myelomonocytic leukemia and several other neoplasms that exhibit increased SHP2 phosphatase activity." (PMID 28460481, 2017). "It is interesting to note that patients with hypomorph mutations in Ptpn11 (Leopard or Noonan syndrome) also display kyphosis, and functional muscle deficits might contribute to the appearance of this phenotype." (PMID 28463680, 2017). "In addition, we verified by exomeanalysis that the patient did not have any pathogenic variants in the genes associatedwith Noonan Syndrome and other rasopathies (PTPN11,SHOC2, KRAS, CBL,SOS1, RAF1, HRAS,NRAS, RASA1, SPRED1,BRAF, MAP2K1, MAP2K2, RIT1 andRRAS)." (PMID 27561113, 2016). "Mutation of PTPN11, which codes for the protein tyrosine phosphatase SHP2, is associated with two clinically related pleomorphic RASopathies (Noonan syndrome and LEOPARD syndrome), both of which are characterized by cardiovascular, craniofacial and skeletal malformations." (PMID 26935104, 2016). "As an example, we propose a novel mechanism to PTPN11 mutations implicated in Noonan syndrome." (PMID 25611800, 2015). "The PTPN11 mutation also appeared to be heterozygous based on variant allele fraction and resulted in a F285S substitution that corresponds to a gain-of-function mutation implicated in a subset of Noonan syndrome." (PMID 27148573, 2015). "In the absence of SH3BP2 mutation in an individual considered to have Cherubism, genetic screening for mutations in genes implicated in Noonan syndrome (PTPN11, SOS1, RAF1, KRAS, NRAS, and BRAF), NF1, and craniofacial cutaneous syndrome (BRAF, MAP2K1) should be undertaken." (PMID 25409853, 2014). "SNPs in the PTPN11 locus are considered to be a cause of Noonan syndrome and LEOPARD syndrome." (PMID 25123136, 2014). "For example, Tartaglia and colleagues assessed PTPN11 (SHP2) mutations by comparing somatic mutations in juvenile myelomonocytic leukaemia (JMML) with Noonan syndrome germline mutations, and they identified a greater activation of the RAS/MAPK activation for the JMML‐associated mutations." (PMID 24803665, 2014). "For example, mutations in the N-SH2 domain in PTPN11 were found to cause Noonan-syndrome." (PMID 24305467, 2013). "Over 50% of cases of Noonan syndrome involve a mutation in the PTPN11 gene." (PMID 22011734, 2011).
Noonan syndrome (continued). "Interestingly, germline PTPN11 mutations have been identified in patients with Noonan syndrome, juvenile myelomonocytic leukaemia, and paediatric acute leukaemia." (PMID 20700123, 2010). "However it should be noted that the nature of somatic JMML-associated PTPN11 mutations differ from the germline mutations identified in Noonan syndrome in that JMML-associated PTPN11 alleles usually encode stronger gain-of-function mutant proteins." (PMID 19737390, 2009). "Additionally, PTPN11 mutations exhibit a male predilection in Noonan syndrome." (PMID 41294667, 2025). "Mutations in the PTPN11 gene cause large clinical phenotypic variability, so milder mutations in the PTPN11 gene may result in less severe cases that are insufficient to meet the clinical diagnostic criteria for Noonan syndrome." (PMID 37605180, 2023). "Finally, activating mutations of the Tyrosine phosphatase SHP-2 (encoded by Ptpn11 gene) in MSCs and osteoprogenitors, already found in Noonan syndrome and associated with an increased risk of leukemic transformation, induce juvenile myelomonocytic leukemia-like myeloproliferative neoplasm in mice." (PMID 31709192, 2019). "We report the first case eosinophilic gastroenteritis in a female patient with Noonan syndrome with a missense variation in the PTPN11 gene." (PMID 40514730, 2025). "Noonan syndrome is a RASopathy caused predominantly by genetic variants encoding the SHP2 protein (e.g., PTPN11, SOS1, RAF1), ultimately leading to hyperactivation of the RAS-MAPK pathway." (PMID 41001496, 2025). "Clinically related Noonan Syndrome (OMIM: 163950), mutation in PTPN11 also reported in patient with exomphalos." (PMID 39319771, 2025). "Multiple gene variants can cause Noonan Syndrome/NSML, including PTPN11, BRAS, and RAF1, with PTPN11 variants being the most common one." (PMID 39898109, 2025). "We herein present the first known case of eosinophilic gastroenteritis in Noonan syndrome with a variation in the PTPN11 gene." (PMID 40514730, 2025). "Rare pathogenic variants in the PTPN11, KRAS, SOS1 and RAF1 genes are the main molecular causes of Noonan syndrome (NS)." (PMID 40041314, 2025). "Noonan Syndrome and Noonan Syndrome with multiple lentigines (NS and NSML, MIM*151100) result from gain-of-function mutations in PTPN11)." (PMID 38540404, 2024). "Gain-of-function (GOF) mutations in PTPN11, encoding SHP2, a cytosolic protein tyrosine phosphatase positively controlling RAS function, underlie approximately 50% of Noonan syndromes (NS), the most common RASopathy." (PMID 38594640, 2024). "There are mutations that are identified on PTPN11 gene which encodes the SHP2 phosphatase, identified in several diseases, as such leukemia, solid tumors, Noonan syndrome and LEOPARD syndrome." (PMID 38739228, 2024). "Pathophysiologically relevant conditions will be situations of low integrin–collagen interaction (including low integrin expression), altered PTPN11 activity such as in Noonan syndrome patients, and partial interference in platelet GPVI activity." (PMID 38236412, 2024). "The following diseases were found in two or more cases: Joubert syndrome (IFT74/CPLANE1, n = 2) and Noonan syndrome (PTPN11/KRAS, n = 3)." (PMID 37895220, 2023). "Noonan syndrome is a cluster of monogenic conditions involving several genes in the RAS-MAPK pathway (PTPN11, SOS1, SHOC2, MAP2K1/2 and KRAS in the included paper)." (PMID 36729042, 2023). "Src homology-2 containing protein tyrosine phosphatase (SHP2), encoded by PTPN11, has been proven to participate in bone-related diseases, such as Noonan syndrome (NS), metachondromatosis and osteoarthritis." (PMID 36768520, 2023).
Noonan syndrome (continued). "Mutations associated with Noonan syndrome alone include CBL, BRAF, KRAS, LZTR1, MAP2K1 (MEK1), NRAS, PTPN11, RAF1, RIT1, SOS1 and SOS2." (PMID 38550930, 2023). "Somatic pathogenic variants in genes of the RAS/MAPK signaling pathway, in turn, are causative for RASopathies such as Noonan syndrome (BRAF, MAP2K1, PTPN11, or RAF1 variants), Costello syndrome (HRAS variants) as well as other Noonan-like syndromes." (PMID 38835734, 2023). "Mutations in 16 genes, including PTPN11 (50%), SOS1 (20%) and RAF1 (5%–15%), have been linked to the development of Noonan syndrome." (PMID 37525886, 2023). "In 2001, PTPN11 was identified as the first Noonan syndrome gene and is responsible for the majority of Noonan syndrome cases." (PMID 38254922, 2023). "Comparison of the lipid profile between patients with Noonan syndrome, Mazzanti syndrome and PTPN11 genotype and the general population." (PMID 37588986, 2023). "Comparison of the lipid profile between patients with Noonan syndrome, and the PTPN11 genotype subgroup to Mazzanti syndrome subjects." (PMID 37588986, 2023). "Ptpn11 mutations lead to increased SHP2 enzymatic activity and altered activation of the Ras/RAF/ERK signaling cascade responsible for Noonan syndrome (NS)." (PMID 35091552, 2022). "Rarely, germline mutations in PTPN11, encoding the phosphatase SHP2, and in SOS1, encoding the guanine nucleotide exchange factor SOS1, have been observed in patients with Noonan syndrome, who subsequently developed ALL." (PMID 35294722, 2022). "Mutations within the Ptpn11 gene locus encoding SHP2 promote tumor progression and have been associated with Noonan syndrome, juvenile myelomonocytic leukemia (JMML) and various other cancers." (PMID 35983034, 2022). "In 2001, PTPN11 was the first gene connected to Noonan syndrome, and until now, at least 20 other genes have been discovered." (PMID 35407641, 2022). "Reportedly, INS and LEP are closely related to obesity, while PTPN11 was identified in the studies of histiocytic sarcoma and Noonan syndrome." (PMID 35529938, 2022). "Eleven patients with Noonan syndrome with lymphatic abnormalities (5 female, 6 male; 7 infants, 4 adults; mean age 10.8 ± 16.4 years) were identified (PTPN11 n = 5/11 [45.5%], RIT1 n = 5/11 [45.5%], KRAS n = 1/11 [9%])." (PMID 35778409, 2022). "This murine model (Ptpn11 D61G/+) not only reproduces several Noonan syndrome characteristics, but also allows for the understanding of the molecular process involved in the development of these features, in a tissue specific context." (PMID 34149626, 2021). "PTPN11 variant carrier, JM155, has a diagnosis of APAH-CHD associated with Noonan syndrome and the c.182A>G variant is known to be pathogenic in Noonan syndrome." (PMID 33971972, 2021). "A notable exception is PTPN11 involved in the Ras/MAPK signal transduction pathway, the most common gene associated with the autosomal dominant developmental disorder Noonan syndrome." (PMID 34064836, 2021). "Normal SHP2/PTPN11 function seems to act as IHH suppressor, and experiments in mice have documented decreased IHH levels in Noonan syndrome caused by germline activating mutations in PTPN11." (PMID 32404184, 2020). "In preclinical models, PTPN11, the gene responsible for 50% of cases of Noonan Syndrome, regulates neurogenesis and is required for neuronal process extension." (PMID 32341405, 2020). "NS and Noonan syndrome with multiple lentigines (NSML, MIM *151100) are the result of a gain-of-function mutation in PTPN11." (PMID 32164556, 2020). "A neurofibromatosis-Noonan Syndrome (MIM 601321) was reported and linked to variants in NF 1, but also to the co-occurrence of independent variants in NF1 and PTPN11 in the same patient." (PMID 31370276, 2019).
Noonan syndrome (continued). "Individuals with Noonan Syndrome (MIM: 163950) comprise ~50% of all RASopathy cases and mutations have been observed in multiple genes, including PTPN11/SHP2, SOS1, SHOC2, KRAS, NRAS, LZTR1 (MIM: 600574), RAF1/CRAF, and MAP2K1/MEK1." (PMID 31017896, 2019). "Pathogenic gain-of-function variants in RAF1—among other genes including PTPN11, SOS1, and KRAS—cause Noonan syndrome." (PMID 30597917, 2018). "Gain-of-function mutations in the PTPN11 gene, encoding SHP2, lead to Noonan syndrome, juvenile myelomonocytic leukaemia (JMML), myelodysplastic syndrome, B cell ALL, and AML." (PMID 29940987, 2018). "The rare genetic disease LEOPARD syndrome, a variant of Noonan Syndrome, given the similarities in characteristic symptoms, is also caused by germline mutations in PTPN11; however, these missense mutations inactivate SHP2." (PMID 30208623, 2018). "To exemplify the PAD gene list, we studied the tyrosine phosphatase PTPN11 where substitutions lead to the congenital Noonan Syndrome, a developmental disorder." (PMID 25611800, 2015). "This corroborates the finding that patient’s with Costello Syndrome (HRAS germline mutation), Noonan Syndrome (NRAS, KRAS, PTPN11 germline mutations) and Neurofibromatosis (NF1 germline mutation) all have increased risk of developing fusion-negative RMS." (PMID 25768946, 2015). "We describe pathogenic copy number variations in two individuals, a 24 Mb duplication of 12q24 containing PTPN11 resulted in apparent Noonan syndrome, while the 183 kb deletion of 10q25.2 including SHOC2 contributed to atypical Noonan-like syndrome." (PMID 24739123, 2014). "Missense mutations in the PTPN11 gene, which encodes the SHP-2 protein tyrosine phosphatase, are responsible for 50% of cases of Noonan syndrome and 95% of cases of LEOPARD syndrome in humans." (PMID 24077964, 2013). "Later, mutations of the PTPN11 gene and the SOS1 gene were identified in patients with Noonan syndrome." (PMID 22640403, 2012). "There are mutations at components of the Ras/Raf/MEK/ERK pathway in the related Costello and Noonan syndromes, including: SOS, and PTPN11 (Shp2) in Noonan syndrome and HRAS mutations in Costello syndrome." (PMID 21422497, 2011). "However, non-penetrance is not restricted to the mutations we described, but is, rather, a common feature in most, if not all, of the described genes that may cause CHD in humans such as PTPN11 in Noonan Syndrome, KCNQ1 in Long QT Syndrome and troponin T in Familial Hypertrophic Cardiomyopathy." (PMID 19886994, 2009). "Twelve patients had PTPN11-related Noonan Syndrome, and exon 3 emerged as a recurrent hotspot." (PMID 41292581, 2025). "Additionally, eight were syndromic patients: four with Noonan syndrome (PTPN11 and biallelic LZTR1), two with Danon disease (LAMP2), two with Carvajal syndrome (DSP), and one with atypical glycogen storage disease (PRKAG2)." (PMID 40642871, 2025). "The whole exome sequencing found a heterozygous variation in the PTPN11 gene (c.124A>G, p.Thr42Ala; chr12-112884189 A>G, NM_002834.5, rs397507501), confirming Noonan syndrome 1 (Phenotype MIM number: 163950, Location 12q24.13, Gene/Locus MIM number 1768762.2.4)." (PMID 40507736, 2025). "Unlike Noonan syndrome (PTPN11 mutations), ZNF292 cases rarely exhibit facial dysmorphism or congenital heart disease, while their normal IGF‐1 levels distinguish them from GH deficiency." (PMID 40777882, 2025).